VIM (vimentin)
Diseases named in the same sentence as VIM in open-access papers (continued):
Sharing a sentence is not in itself a finding about the gene and the disease.
cancer (continued). "The type III intermediate filament, vimentin, is a key biomarker of EMT which is normally expressed in mesenchymal cells but is upregulated during cancer metastasis." (PMID 38907776, 2024). "Cancer cells often exhibited EMT and other characteristics during metastasis, and vimentin contributes to EMT by changing cell shape and movement." (PMID 38389041, 2024). "Vimentin is a well-established marker of EMT and it serves as a crucial component for the initiation of cancer invasion and metastasis cascades." (PMID 38191501, 2024). "Vimentin protein is a canonical EMT marker in mesenchymal cells and is involved in cancer progression (Kidd, Shumaker & Ridge, 2014)." (PMID 38737746, 2024). "Cancer cells undergo EMT, which involves phenotypic changes characterized by altered expression of E-cadherin, N-cadherin, and vimentin during the early stages of metastasis." (PMID 38732748, 2024). "In cancer cells, during the EMT process, the expression of mesenchymal markers (e.g., vimentin, N-cadherin, and vitronectin) and proteins, such as matrix metalloproteinases, is activated." (PMID 38611032, 2024). "The expression levels of E-cadherin and vimentin, two documented metastatic factors, are regulated by PKIB, thus demonstrating an impact of PKIB expression on cancer metastasis." (PMID 38731883, 2024). "Vimentin promotes metastasis by contributing to EMT, enhancing cancer cell migration and invasion, increasing resistance to apoptosis, and aiding in the colonization of distant organs." (PMID 38685125, 2024). "After infection, we quantified changes in the cellular cancer phenotypes, the gene expression levels of some cancer markers, including Ki-67, BCL-2, VIM, MMP9, and VEGF, and proinflammatory cytokines." (PMID 39427065, 2024). "As the crucial role of EMT in the migration and invasion of epithelial cell‐derived malignant tumors, we examined the expression of mesenchymal markers (N‐cadherin, ZEB1, Vimentin, Snail) and epithelial marker (E‐cadherin)." (PMID 38733179, 2024). "These proteins include vimentin, which is upregulated in cancer cells undergoing an EMT, and keratins, which have an altered expression in many cancers." (PMID 38398174, 2024). "It has been established that vimentin was one of the main drivers of EMT, by which cancer cells obtain special phenotypes to invade the extracellular matrix and withstand the external sheer forces during metastasis." (PMID 39272902, 2024). "For optimal recovery of cancer cells, three epithelial-specific markers (EpCAM, EGFR, and cytokeratin) and one EMT marker (Vimentin) were added." (PMID 38469233, 2024). "Ca Ski RT_A also exhibited decreased levels of the expression of VIMENTIN, a type III intermediate filament that is expressed in the mesenchymal cells and upregulated during cancer metastasis." (PMID 38399969, 2024). "These marker genes represent multiple malignant phenotypes of cancer, including tumorigenesis (EGFR, MYC), cell invasion (ITGB1 and VIM), and angiogenesis (VEGFA), among others." (PMID 38191424, 2024). "Furthermore, the expression of vimentin in the lungs was found to be significantly reduced in mice receiving p190RhoGAP siRNA and δD910A/D910A macrophages compared with mice receiving p190RhoGAP siRNA and WT macrophages, reflecting decreased invasion of cancer cells." (PMID 38182748, 2024). "Our Mass Spectrometry analyses revealed the interaction between HNRNPC and Vimentin, an important cytoskeleton protein involved in epithelial-to-mesenchymal transition (EMT) and cancer metastasis." (PMID 38184608, 2024). "The intermediate filament protein vimentin regulates cell adhesion to the extracellular matrix, cell shape, and motility, all key for EMT-mediated cancer invasion." (PMID 39796712, 2024). "Following treatment with the encapsulated EO, a notable reduction in the expression of VIM, SLUG, SNAIL, and JUN, which are promoters of cancer cell invasion, was seen." (PMID 40259961, 2024).
cancer (continued). "The high expression of vimentin indicates the progression of EMT and the occurrence of cancer cell metastasis and invasion." (PMID 37989078, 2024). "Regarding immunohistochemical staining, most sRCC stain positive for AE1/AE3, vimentin, CK OSCAR, PAX-8, and epithelial membrane antigen owing to the epithelial origin of the cancer." (PMID 39564030, 2024). "As results indicated, IR‐TAM@Alb exhibited the ability to impede cancer cell invasion in both 4T1 cells and MCF‐7 cells in vitro by transwell migration assay through the upregulation of E‐cadherin and down‐regulation of Vimentin." (PMID 38715382, 2024). "Vimentin is a key marker of EMT and plays a significant role in the aggressive phenotype of cancer cells, particularly in processes such as cancer progression, metastasis, and chemoresistance." (PMID 39796130, 2024). "E-cadherin and Vimentin are markers of epithelial mesenchymal transition (EMT), and which are involved in cancer cell metastasis." (PMID 39247610, 2024). "Detection of differential markers subtyped the cells of mesenchymal origin (vimentin, desmin, cadherin-11, podoplanin, CD74, S100A4, CD44, FAP), which vary according to the functional differentiation and specialization in sites of cancer tissue." (PMID 39575252, 2024). "These inhibitory effects would disrupt the cancer cells’ metabolism (by reducing GLUT1) and their invasion and migratory abilities (by reducing MMP7, CXCR4, LOXL2, CXCL12, and vimentin)." (PMID 39272902, 2024). "Since cancer cells need to survive even in the absence of proper cell adhesion in the bloodstream during their journey to distant metastatic sites, we hypothesized that the survival benefits of vimentin may reduce programmed cell death of cancer cells, or anoikis, caused by the absence of adhesion." (PMID 38915055, 2024). "The functional assays depicted a suppression of cancer cell proliferation, colony formation, migration, no change in apoptosis and corresponding EMT markers (CK18 and VIM), predicated on DUSP8 upregulation." (PMID 38396293, 2024). "However, it remains unclear whether vimentin is involved in cancer cell nuclear dysmorphia." (PMID 39542246, 2024). "Therefore, we stained adjacent sections for E-cadherin, vimentin, Slug, laminin 5, PRMT1, and PRMT5 and investigated whether the expression levels of these molecules and/or those of MST2 and YAP1 were associated with the cancer cell invasion pattern." (PMID 38444414, 2024). "Our analyzis identified shared markers among the fibroblasts from both carcinoma types, notably DCN, VIM, ACTA2, CXCL12/14, and COL1A1, which were prominent markers, characteristic of these cells." (PMID 39796089, 2024). "Our results confirmed that hypoxia treatment upregulated the expression of vimentin and KRT16 while downregulating the expression of KRT18 in both cancer cell types, indicating the upregulation of EMT and metastasis." (PMID 37780810, 2023). "Kv3 channels participate in cancer cell proliferation, migration, and metastasis via the AKT signaling pathway and vimentin, which is involved in cell migration and EMT." (PMID 37408210, 2023). "Dimensionality reduction and graph-based clustering analysis identified 3 cancer cell clusters (clusters 1-3) and 3 CAF clusters (clusters 4-6), marked by expression of EPCAM and Vimentin respectively." (PMID 37261365, 2023). "Molecularly, cancer cells present in Cluster 8 displayed elevated expression of CD97, pNF‐κB, and HLA‐DR, and low CD90 and Vimentin levels." (PMID 36550781, 2023). "Analysis of the CRC dataset from the cancer genome atlas (TCGA) demonstrated a positive correlation between THBS1 and mesenchyme-related genes (VIM and FN1) and pan-myeloid markers (CD14 and CD33)." (PMID 37749092, 2023). "While EMT is a crucial process in cancer progression, our results show that AA has little effect on the majority of EMT marker proteins, including E-cadherin, N-cadherin, β-catenin, and vimentin." (PMID 37375849, 2023).
cancer (continued). "In this study, we have selected and comprehensively evaluated the expression of four commonly known EMT markers (E-cad, N-cad, VIM, TGFβ1), and four unconventional EMT markers (α-SMA, AKR1B1, ITAV, G6PD), less studied in cancer in relation to the EMT process." (PMID 37174052, 2023). "Alpha smooth muscle actin (α-SMA), another cytoskeletal marker like VIM, has been known to contribute to EMT in cancer." (PMID 37174052, 2023). "In this way, fibroblastic overexpression of vimentin regulates CAF invasion, and cancer cell-CAF interaction results in decreased spheroid circularity." (PMID 38313431, 2023). "AKT signaling, known to be active in cancer cells, has been shown to mediate lncRNA VAL binding to Vimentin to eliminate Trim16-dependent Vimentin polyubiquitination and degradation and promote LAD invasion and metastasis." (PMID 36969045, 2023). "In cancer, vimentin is well known for being an important marker of epithelial-mesenchymal transition (EMT), a process critical for cancer invasion and metastasis cascades." (PMID 36631457, 2023). "Therefore, while other groups have found that vimentin deficiency impairs function in cancer-associated fibroblasts and immune cells such as macrophages and T cells, a vimentin-expressing microenvironment is not sufficient to promote metastasis in the time frame evaluated." (PMID 37161053, 2023). "Vimentin belongs to the class of type III intermediate filaments, forming homopolymers of vimentin monomers, and it is expressed in most cancer and precursor cells." (PMID 37051546, 2023). "Vimentin is a protein marker for EMT, a process in which cancer cells acquire a migratory and invasive phenotype." (PMID 37915048, 2023). "We conducted an oncology protein array to measure 84 major cancer-related proteins in both A549 cells and A549 EVs and found that EpCAM, EGFR, Dkk-1, Galectine-3, Endostatin, E-Cadherin, FGF basic, Vimentin, and progranulin are the top nine hits." (PMID 36834913, 2023). "Sixty percent of the tumors analyzed expressed high levels of Vimentin and PGP9.5 [also known as Ubiquitin C-terminal hydrolase L1 (UCHL1)], suggesting the presence of cancer cells undergoing EMT." (PMID 38067168, 2023). "Cancer cell growth is primarily facilitated by the EMT marker proteins e-cadherin and vimentin, and SIRT1 is connected to the production of invasive proteins in tumors." (PMID 36899911, 2023). "There were various cancer-related genes involved in TGFβ signaling such as ZEB1, Snail1 and Vimentin that played vital roles in the malignant progression of PC." (PMID 37322017, 2023). "Vimentin, a type III intermediate filament protein, is typically found in mesenchymal cells and is often overexpressed in cancer cells." (PMID 37242510, 2023). "Anti-cancer-activity-related proteins were altered, including CLTA, HSPA9, HIST2H2BF, KRT18, HINT1, DSP, and VIM." (PMID 37371778, 2023). "We therefore evaluated the expression of a panel of epithelial (KRT5, 7, 8, 18, and CDH1), mesenchymal (VIM, FN1, SNAI1, TWIST1, COL1A1, and PRRX1), and cancer stem cell (ALDH1A2, ALDH7A1, CD44, and CCND1) markers in all samples." (PMID 36980717, 2023). "P0825 expressed high levels of cancer markers KRT19 and EpCam, cancer stem marker Sox9, Hippo oncogenic co-activator Yap1, and EMT marker Vimentin." (PMID 36865791, 2023). "In diverse cancers, levels of p-ERK1/2 were correlated with upregulation of vimentin, snail, N-cadherin, and MMP-9, with a decrease in E-cadherin expression." (PMID 37033630, 2023). "During metastasis, cancer cells undergo an EMT, which increases the expression of vimentin, and the expression of E-cadherin is switched to that of N-cadherin." (PMID 37047791, 2023). "Our results on radiation-induced expression of vimentin in CC cells support the literature data on an increase in the expression level of various EMT markers in cells of cervical and other cancers after fractionated irradiation under experimental conditions." (PMID 36834676, 2023).
cancer (continued). "Dysregulated expression of the phosphatase has also been found to impact the metastatic dissemination of cancer cells by regulating the levels of key members of the EMT pathway, including E-cadherin and Vimentin." (PMID 35361144, 2022). "Our EMT+ subtype exhibit elevated markers VIM, SNAI1, and ZEB1, consistent with our pan-cancer analysis and with known molecular features of epithelial-mesenchymal transition." (PMID 35912202, 2022). "NETs enhance cancer cell migration and induce EMT; downregulation of E-cadherin and upregulation of vimentin expression." (PMID 35574410, 2022). "Summary of top four selected genes (COL5A2, ITGAV, SPARC and ACTA2) which were correlated with EMT signature in 32 pan cancer cohorts was presented in radar graphs, and the well-known CDH1 (Epithelial) and VIM (Mesenchymal) genes were included as controls." (PMID 35046456, 2022). "The acetylation of vimentin and other EMT-related proteins affects the migratory capacity and the metastatic properties of various types of cancer cells." (PMID 35359446, 2022). "Compared with placebo control, bosentan treatment did not significantly change the mRNA levels of Cyclin D1, MMP2, Vimentin and ETB under conditions of fibrocyte depletion, except leading to a slight downregulation of mRNA expression of ETA in cancer cells." (PMID 36241617, 2022). "These include: CDH1, MUC1, THBS4, and MSLN for PEs related to cancer; ADA2, CXCL10, and WARS for TB-PEs; CRP, S100A9, and VIM for parapneumonic PEs; and C9, LDHA, HPX, LDHB, and C3 for benign-PEs." (PMID 35197508, 2022). "Among the EOC tissues examined, CXCR4 expression correlated strongly with expression of proteins related to the epithelial-mesenchymal transition (EMT) and cancer stem cell (CSC), including vimentin, N-cadherin, E-cadherin, CD44, CD133, and NANOG." (PMID 35681259, 2022). "We chose keratin 19, histone H3, vimentin, and cytochrome c oxidase subunit 4 (COX IV) as target proteins, as they are related to cancers and used as cancer markers." (PMID 35513404, 2022). "Epithelial‐mesenchymal transition (EMT) cascades have been documented to participate in cancer cell infiltration and migration; thus, we assessed the effects of MYPT1 on EMT by exploring the expression of N‐cadherin, E‐cadherin and Vimentin." (PMID 36106411, 2022). "It has been reported that most of the 8 ARGs (VIM, UFM1, TSC2, SRC, MEFV, CTTN, CFTR and CDKN1A) are related to cancer." (PMID 35121801, 2022). "We subsequently performed IHC staining to validate the expression of VIM and TGFB1 in cSCC in a clinical cohort that comprised 16 patients with cancer progression events, from primary tumors to cSCCs with single or multiple recurrences." (PMID 36438481, 2022). "Cancer cells in CIPCOs showed increased expression of ZEB-1, fibronectin, and vimentin compared with the levels in PCOs." (PMID 35565206, 2022). "Some of these proteins, specifically RhoA, Vimentin, LDHA and are very important proteins in the development and progression of cancer." (PMID 36313672, 2022). "We then analyzed a smaller cohort of TNBC patients from Moffitt Cancer Center (N = 129) for the expression of TTK, active (p-TBK1), Ki-67, Vimentin, and E-cadherin in NHB and NHW patients." (PMID 36494865, 2022). "Cancer cells undergoing EMT usually show down-regulation of E-cadherin, while the morphological changes are usually accompanied with up-regulation of vimentin and N-cadherin." (PMID 36338704, 2022). "Vimentin, a type III intermediate filament, normally expressed in mesenchymal cells, is considered a biomarker for EMT, and it is upregulated during cancer metastasis." (PMID 36185255, 2022). "At the same time, vimentin is not only marker of EMT and can itself play different roles in increasing the metastatic potential of cancer cells." (PMID 36278174, 2022).
cancer (continued). "The upregulation of MMPs (MMP2, MMP9, and MMP13) was also reported in cancers overexpressing IL-32 along with other EMT markers including vimentin, Slug, Snail, and ZEB1, as well as they are well known for their contribution to cancer metastatic." (PMID 35281008, 2022). "Similar to Snail, Twist1 represses the epithelial marks such as E‐cadherin, α‐catenin, γ‐catenin and upregulates mesenchymal marks including vimentin, fibronectin, N‐cadherin, leading to EMT and cancer progression." (PMID 35601657, 2022). "For example, the ionophore antibiotic salinomycin upregulates the E-cadherin gene while reducing the expression of vimentin in CD133+ colorectal cancer cells and restoring cancer cell sensitivity to chemotherapy." (PMID 36313710, 2022). "Vimentin is also regarded as a biomarker of EMT and is often overexpressed when cancer cells acquire their mesenchymal phenotype." (PMID 35898472, 2022). "Regarding the role that curcumin treatment plays in decreasing the high abundance, or high expression level of cancer EMT biomarkers, previous observations pointed to two important targets, fibronectin, and vimentin." (PMID 35873564, 2022). "Upon autophagy inhibition, the levels of mesenchymal markers including VIM (vimentin) and CDH2/N-cadherin undergo downregulation and further confirm the role of autophagy in cancer metastasis." (PMID 35317831, 2022). "FYN overexpression significantly inhibited A549 cell viability, invasion, migration, and angiogenesis, accelerated cell apoptosis, and inhibited E-cadherin, vimentin, Snail, and PI3K/AKT protein expression in cancer cells." (PMID 36276113, 2022). "Other biomarkers of the Wnt cascade, E-cadherin, vimentin, Adenomatous polyposis coli (APC), Snail and N-cadherin were revealed to be of importance in the carcinogenesis of other cancer types, such as oral squamous cell carcinoma." (PMID 35873564, 2022). "Previous studies have shown that E-cadherin, N-cadherin, vimentin, MMP2, and MMP9 expression levels can indicate EMT and invasion in various cancers." (PMID 35885009, 2022). "One of the most important mechanisms in cancer metastasis is EMT occurring due to decrease in CDH1/E-cadherin levels and increase in CDH2/N-cadherin and VIM levels." (PMID 35317831, 2022). "Although different markers were used to evaluate EMT in cancers, there was a consistent CCR7-induced increased activation of Slug, N-cadherin, TGF-β, vimentin, phospho-ERK, phospho-Akt, MMP-2, MMP-9 and Snail attenuation of E-cadherin." (PMID 35203305, 2022). "A decrease in N-cadherin, vimentin and Snail expression and an increase in E-cadherin protein content promote the EMT process and increase the invasion and metastasis of cancer cells." (PMID 35413833, 2022). "Vimentin, MMP9, FN1, and N-Cadherin are the well-known genes that have the main contribution to metastasis and EMT (Epithelial-to-mesenchymal transition) in cancer." (PMID 35193569, 2022). "In our previous work in this model, we demonstrated cancer-secreted OPN acts through the transcription factor MZF1 to express the myCAF phenotype corresponding with increased α-SMA, VIM, and TEN-C." (PMID 36284815, 2022). "Vimentin, a type III intermediate filament that forms the cytoskeletal microtubules and microfilaments, has been a suspected culprit antigen for SLR in cancer patients." (PMID 36059841, 2022). "Cancer cells incubated with CCL19 (50 ng/ml) or CCL21 (100 ng/ml) showed increased expression of N-cadherin and vimentin and decreased expression of E-cadherin." (PMID 36268282, 2022). "In contrast, the expressions of N-cadherin and Vimentin proteins was decreased, indicating the lower EMT ability of cancer cells." (PMID 36292671, 2022).